HIF1A (hypoxia inducible factor 1 subunit alpha)
Diseases named in the same sentence as HIF1A in open-access papers (continued):
Sharing a sentence is not in itself a finding about the gene and the disease.
tumor (continued). "As tumour angiogenesis is mainly initiated by HIF‐1α/VEGF signalling, inhibition of HIF‐1α is likely to influence the tumour vasculatures." (PMID 39757131, 2025). "HIF1A is a core hypoxia-inducible transcription factor, and its function and metabolic role in tumor regulation continue to be a hot topic of research." (PMID 41198650, 2025). "In macrophages, GLUT1 and glycolysis can be upregulated through the tumor-derived exosome (TDE)/TLR2/NF-κB/HIF-1α signaling pathway, leading to increased cellular lactate, which subsequently feeds back on NF-κB to further enhances PD-L1 expression." (PMID 41373022, 2025). "EZN-2208, an inhibitor of HIF-1α, has displayed anti-tumor activity both as monotherapy and in combination with bevacizumab in phase I clinical trials involving refractory solid tumors." (PMID 41383608, 2025). "From the substrate standpoint, either MYC activation or HIF-1α stabilization in tumor cells markedly upregulates the expression of oncogenic substrates such as HIF-1α and METTL14." (PMID 41583428, 2025). "Within 768-O tumor spheroids, NK cells displayed a higher degree of hypoxia and expression of HIF1α, and inhibition of HIF1α resulted in higher NK cell infiltration into 786-O spheroids." (PMID 40736709, 2025). "Through the activation of HIF-1α, hypoxia alters immune responses by promoting the expression of immune checkpoint molecules such as PD-L1 on tumor and immune cells, leading to T cell exhaustion." (PMID 39981236, 2025). "Collectively, HIF-1α orchestrates the adaptation of tumor cells to hypoxia by selectively inducing its targets according to the severity of hypoxia." (PMID 40171017, 2025). "It has been shown that it can inhibit PHD2 activity, leading to stabilizing HIF-1α in normoxic oxidative tumor cells." (PMID 40358197, 2025). "In liver cancer, the activation of the Hypoxia-Inducible Factor 1α (HIF-1α) pathway often promotes tumor progression." (PMID 40698038, 2025). "Tumor hypoxia critically impairs NK cell function, where the upregulation of hypoxia-inducible factors (HIFs), comprising oxygen-sensitive alpha subunits (HIF-1α, HIF-2α, HIF-3α) and constitutive beta subunits (HIF-1β), triggers detrimental cellular changes." (PMID 41511303, 2025). "Hypoxia-induced abnormal accumulation of HIF-1α within the tumor microenvironment drives malignant progression through the regulation of metabolic reprogramming." (PMID 41515171, 2025). "Rhaponitin (Rha) possesses anti‐tumor activity and mediates the transcriptional activity of hypoxia‐inducible factor (HIF)‐1α that affects cisplatin (Cis) resistance." (PMID 40608530, 2025). "TAMs have been observed to modulate HIF-1a expression in tumor cells and the tumor endothelium subsequent to low-dose radiotherapy." (PMID 40356601, 2025). "It is highly expressed in tumor cells, and its dimeric form can act as a coactivator of HIF-1α, promoting the stability of HIF-1α." (PMID 40948745, 2025). "Silibinin’s effects on HIF-1α also suggest that it can modulate the tumor microenvironment, improving immune cell function and tumor recognition." (PMID 40490812, 2025). "Local hypoxia, in turn, creates hypoxia-inducible factors (HIFs), particularly HIF-1α; this promotes a pro-inflammatory and pro-tumorigenic environment through angiogenesis, metabolic reprogramming, and other processes that support tumor growth and survival." (PMID 40722646, 2025). "The pH level of internal and external environments of tumor cells is regulated by HIF-1α in diverse manners." (PMID 40171017, 2025). "HIF-1α protein acts as a tumor suppressor and is frequently lost through inactivating mutations, 14q chromosome deletions, HIF-2α acts as an oncogene promoting the expression of its target genes (VEGF, PDGF, CAIX Oct4, among others)." (PMID 40620865, 2025). "Circ_03955 functions as a tumor promoter through the miR-3662/HIF-1α axis, providing new perspectives on the treatment of PDAC." (PMID 40630951, 2025).
tumor (continued). "The results showed a significant increase in HIF1A expression and H3K18la levels in the tumor tissues of the L-2-HG group mice." (PMID 41198650, 2025). "Available evidence suggests that HIF‐1α facilitates drug resistance by enhancing the stemness of tumor cells." (PMID 40608530, 2025). "Research has revealed that O-GlcNAc modification enhances AKT activity, promoting tumor cell proliferation and survival; O-GlcNAc modification strengthens the stability of HIF-1α, promoting tumor cell angiogenesis and metastasis." (PMID 41164182, 2025). "TRAP1-dependent metabolic rewiring in macrophages is mandatory for sustaining this interplay, as a TRAP1-succinate-HIF-1α signaling axis orchestrates their acquisition of tumor-promoting features." (PMID 40877908, 2025). "In contrast, dioscin exerts dual anti-inflammatory and anti-tumor activity through mTORC1/HIF-1α inhibition and PPARγ activation, showing broader applicability in both colitis and melanoma." (PMID 40417220, 2025). "Considering that HIF1α activation occurs under hypoxic conditions commonly observed in solid tumors, we examined hypoxic conditions within three‐dimensional tumor spheroids to simulate the hypoxic microenvironment of tumoral tissue." (PMID 40151834, 2025). "In this study, our results suggest that the HIF-1α/BMAL1/ALDOC pathway functions to enhance anaerobic glycolysis in tumor cells, thus reducing the sensitivity of CRC to L-OHP." (PMID 40535800, 2025). "Hypoxia stabilizes hypoxia-inducible factor 1α (HIF-1α), a key regulator that enhances glycolytic gene expression and promotes tumor survival via the PI3K/Akt/mTOR and NF-κB pathways." (PMID 41476608, 2025). "Hypoxia within the tumor microenvironment (TME) upregulates HIF-1α, which promotes the differentiation of monocytic myeloid-derived suppressor cells (m-MDSCs) into tumor-associated macrophages (TAMs)." (PMID 41425545, 2025). "Based on these in vitro findings, we propose a three-step mechanism for the tumor-suppressive effects of combining HIF-1α inhibition with a ketogenic diet." (PMID 41465202, 2025). "The discovery of this tumor-protecting biochemical pathway advanced our understanding of pharmacological approaches to block the early stages (hypoxia/HIF1A) and late stages (adenosine/A2AR/cAMP) of this signaling axis." (PMID 40125552, 2025). "Emerging HIF inhibitors such as PT2385 (targeting HIF-2α) and the dual HIF-1α/p300 disruptors have shown enhanced specificity and tumour selectivity." (PMID 40806577, 2025). "The upregulation of ONECUT3 in CRC facilitates tumor growth by enhancing the transcriptional activity of HIF-1α through HDAC6-mediated deacetylation." (PMID 40032849, 2025). "HIF‐1α has been demonstrated to increase the malignant transformation potential of various tumours through the regulation of tumour metabolic reprogramming." (PMID 40954549, 2025). "Taken together, these data suggest a critical role of HIF1α-mediated metabolic rewiring in the increased tumor growth and metastasis upon RNF20 LOF in vivo." (PMID 40436847, 2025). "Activated HIF-1α can alter gene expression, promoting angiogenesis, metabolic reprogramming, and epithelial–mesenchymal transition, thereby driving tumor progression and metastasis." (PMID 40429910, 2025). "By reducing tumor hypoxia, HAPs indirectly inhibit HIF-1α activity and enhance the efficacy of ICIs." (PMID 39981236, 2025). "Our experiments confirmed that reducing HIF-1α while increasing CD47 in GBM cells significantly enhances malignant proliferation, colony formation and tumor cell migration, indicating that HIF-1α can modulate GBM characteristics via the CD47 protein." (PMID 39781344, 2025). "HIF-1α-mediated upregulation of PD-L1 on tumor cells and antigen-presenting cells inhibits T cell activation, leading to exhaustion." (PMID 39981236, 2025).
tumor (continued). "Hypoxia, a hallmark of solid tumors, further exacerbates this microenvironment by stabilizing hypoxia-inducible factor 1 alpha (HIF1α), which enhances lactate production, thereby promoting tumor survival and aggressiveness." (PMID 40723225, 2025). "Additional mechanisms of progression include tumor hypoxia and overexpression of HIF-1α, CA9, and VEGF, which increase tumor aggressiveness." (PMID 40805266, 2025). "In vivo results proved the system efficacy as an amplifier of radiotherapy-induced replicative stress, leading to increased DNA damage and reduced tumor hypoxic via HIF-1α downregulation, culminating in tumor volume reduction." (PMID 39885557, 2025). "As an effective PS carrier for targeted PDT with decreased tumor resistance, the created DNA NSs, which had particle sizes between 300 and 350 nm, dramatically suppressed tumor development in mice with cervical cancer through the downregulation of HIF1α." (PMID 41245513, 2025). "Although PRCC‐TFE3 KI/Hif1α KO showed a reduction in both tumor area and number, cystic tubular dilation was still observed in the tissue, suggesting that Hif1α KO does not completely reverse the pathological changes in the kidneys of PRCC‐TFE3 KI." (PMID 39807625, 2025). "Functionally, dual treatment also inhibited cell migration, HUVEC tube formation and VEGF secretion by tumor cells under hypoxia via HIF1α blockade, aligning with canonical HIF1α-VEGF regulation." (PMID 41463265, 2025). "These pathways enhance HIF-1α protein translation and inhibit its degradation, allowing HIF-1α to remain active in oxygen-rich tumor regions." (PMID 41450919, 2025). "The mechanism is based on activation of signaling pathways that promote cell survival, such as PI3K/Akt and MAPK/ERK, and stabilization of the factor HIF-1α, which promotes angiogenesis and hypoxia within the tumor." (PMID 40649317, 2025). "HIF-1α is highly expressed in various digestive system tumor cells and can promote the expression of downstream metalloproteinases (including MMPs and ADAMs)." (PMID 40563539, 2025). "While HIF-1α levels remained unchanged in lung and bone PMN, liver macrophages from MC38 tumor-bearing mice exhibited significant upregulation of both HIF-1α and FABP7 compared to controls." (PMID 40765822, 2025). "Small interfering RNAs can silence the expression of the oncogene HIF‐1α and thereby inhibit tumour growth." (PMID 40954549, 2025). "While HIF-2α is apt to be involved in maintaining stem cell pluripotency and promoting tumor growth, more dramatic than HIF-1α." (PMID 40246814, 2025). "HIF-1α mediates the transcription of proangiogenic factors, enhancing tumor vascularization and metastasis." (PMID 41041327, 2025). "In this sense, the PI3K/Akt/HIF-1α pathway is one of the most important signaling pathways in regulating tumor metabolism through the activity of HIF-1α as a transcription factor." (PMID 40072116, 2025). "In particular, HIF-1α—stabilized by both hypoxia and ROS—further drives glycolytic gene expression, thereby promoting tumor aggressiveness." (PMID 40868256, 2025). "A11, a derivative of 20(R)-panaxotriol, dose-dependently inhibited the transcriptional activity and protein content of HIF-1α and suppressed nuclear aggregation of HIF-1α in HeLa tumor cells." (PMID 41585262, 2025). "In another study, HIF-1α was upregulated in tumor cells in response to doxorubicin enhancing VEGF secretion and synthesis of NO, stimulating tumor angiogenesis." (PMID 40032892, 2025). "Mechanistically, VIRMA is promoting signaling through the STRA6/STAT3 axis, leading to elevated HIF-1α levels, which in turn enhances glycolysis and drives tumor progression." (PMID 40102715, 2025). "HIF-1α further orchestrates CLL cell interactions with tumor microenvironments by regulating chemotaxis and bone marrow/spleen niche adhesion." (PMID 40791591, 2025).
tumor (continued). "Under hypoxic conditions within the primary tumor, HIF-1α in tumor cells is upregulated, translocates to the nucleus, and activates transcription of target genes, including the VEGF gene promoter, leading to increased VEGF expression." (PMID 41463352, 2025). "HIF-1α can inhibit T cell function and boost PD-L1 expression, which is detrimental to anti-tumor immunity and encourages tumor immune escape." (PMID 40917751, 2025). "Hypoxia in the tumor core enhances glycolysis and lactate metabolism through the activation of the HIF-1α pathway, further reinforcing an immunosuppressive state." (PMID 40255400, 2025). "The influence of HIF-1α extends beyond tumor cells to other components of the tumor microenvironment, including immune cells and stromal elements." (PMID 39981236, 2025). "Overall, overactivation of HIF-1α in tumor cells and its impact on lactate accumulation is one of the key factors regulating tumor cells’ adaptation to the hypoxic environment." (PMID 40704062, 2025). "This suggests that pseudohypoxia, along with the tumor microenvironment and the effects of HIF1A activation, leads to increased expression of hypoxia-related genes such as EPO." (PMID 40332447, 2025). "In tumor angiogenesis, HIF-1α regulates the response to hypoxic stress through the switch from aerobic to anaerobic metabolism." (PMID 41008931, 2025). "Conversely, several PTMs of HIF1α play tumor-suppressive roles, inhibiting BC progression and metastatic ability, reducing cell growth, inducing autophagy, or inhibiting different pathways involved in the malignant transformation of BC cells, such as mTOR." (PMID 39942749, 2025). "HIF-1α shows high expression in many malignant tumor cells, and even has expression in some precancerous lesion tissues." (PMID 40458722, 2025). "Tumor angiogenesis occurs through the action of many angiogenic factors, which usually also participate in physiological angiogenesis, such as HIF-1α and angiopoietin-2 (ANG-2)." (PMID 40429943, 2025). "In the tumor protein analysis, the expression of HIF-1α was strongly suppressed in YC-1-treated tumors." (PMID 41465202, 2025). "Despite its crucial role in tumorigenesis, the precise mechanisms governing HIF1α stabilization under varying tumor microenvironmental conditions are not fully understood." (PMID 40701956, 2025). "For example, nanoparticles loaded with acriflavine or siRNA targeting HIF-1α are coated with hypoxia-sensitive polymers that degrade under low oxygen levels, ensuring targeted delivery to hypoxic tumor cells." (PMID 39981236, 2025). "In our model, tumour expansion drives increasing HIF-1α levels, which in turn stimulates VEGF production, and leads to the formation of abnormal, leaky vasculature." (PMID 41463127, 2025). "In ccRCC specifically, glutamine depletion by tumor cells leads to the activation of HIF1α in infiltrating macrophages, thereby promoting IL-23 secretion and contributing to poor clinical outcomes." (PMID 40723891, 2025). "In most cases, HIF-1α seems to have a tumor-suppressive role, supported by its capacity to induce metabolic reprogramming, growth arrest and apoptosis, whereas HIF-2α is considered to have pro-oncogenic roles in inducing growth, pluripotency, and angiogenesis." (PMID 41413686, 2025). "MAO-B promotes tumor angiogenesis via HIF-1α/VEGF pathway to provide nutritional support for LUAD cells." (PMID 41003841, 2025). "The central region of the tumour had higher HIF-1α, corresponding to higher SUVmax, indicating the correlation between FDG uneven distribution and hypoxia." (PMID 39977367, 2025). "HIF1α inhibitors, such as echinomycin, attenuate tumor growth and promote apoptosis in hypoxic GBM cells." (PMID 39859381, 2025).
tumor (continued). "The SUMO E3 ligase Cbx4 also enhances tumor angiogenesis by enhancing HIF‐1α activity and VEGF expression in hepatocellular carcinoma." (PMID 41362701, 2025). "Particular attention will be given to PFKFB4-associated signaling pathways, including its interactions with HIF-1α, regulation of glucose metabolism reprogramming, and promotion of tumor stemness properties." (PMID 40269756, 2025). "High levels of HIF-1α in this context are correlated with higher tumor grades, increased metastasis, and reduced overall survival." (PMID 39757165, 2025). "Other modulators, including FAT1, integrins αvβ3 and αvβ5, HIG2, and GGTI, also regulate HIF-1α expression, contributing to increased tumor cell migration and invasion." (PMID 40800581, 2025). "The correlation between ADC values and HIF-1α expression showed different results in different tumor types." (PMID 40809031, 2025). "Hypoxia‐inducible factor‐1α (HIF‐1α), a key transcriptional regulator, becomes activated in hypoxic tumor microenvironments." (PMID 40772466, 2025). "HIF-1α functions as a transcription factor that modulates the expression of various genes essential for tumor growth, metastasis, and drug resistance." (PMID 40136686, 2025). "Specifically, under normal oxygen, HIF-1α is degrade, making tumor cells vulnerable to immune surveillance." (PMID 41048631, 2025). "The glycolytic metabolite lactate, produced by the tumor cells, stabilizes HIF-1α, which in turn induces VEGF expression and promotes M2-like polarization of TAMs." (PMID 40109347, 2025). "HIF-1α has been reported to be related to the production of soluble NKG2D ligand molecules or to reduce the expression of NKG2D ligands on tumor cell surfaces and is a key factor in mediating tumor immune escape mechanisms against NK cells and others." (PMID 40563539, 2025). "HIF-1α plays a pivotal role in cellular responses to hypoxia and is frequently overexpressed in cancer, contributing to tumor progression, metastasis, and therapy resistance." (PMID 41392176, 2025). "Recent research indicates that various cancer modalities, including radiotherapy, photodynamic therapy, and hyperthermia, can elevate HIF-1α levels within tumor cells." (PMID 40032892, 2025). "In the exosome cohort CXCL12 expression was strongly correlated with EGFR status, CD44v6 was associated with tumor stage, TTF-1 expression & chromogranin protein expression and HIF1A & TGFBR2 showed positive correlation with CEA expression & CK20 expression." (PMID 38877052, 2024). "For example, HIF-1α is a critical regulatory factor contributing to drug resistance in tumor cells under hypoxic conditions." (PMID 39845318, 2024). "The oxygen deficiency negatively influences the immune response against the tumor via the transcriptional factor HIF-1α, which has been shown to activate the expression of PD-L1 on the surface of malignant cells in renal cell carcinoma." (PMID 39650654, 2024). "Among others, VEGF/VEGFR, angiopoietin (ANGPT), endothelial nitric oxide synthase (eNOS or NOS3), and hypoxia-inducible factor-1α (HIF-1α) signaling play an important role in regulating tumor angiogenesis." (PMID 38396873, 2024). "HIF-1α is required for effector states in CD8+T cells, and the loss of HIF-1α in CD8+T cells reduces tumor invasion and tumor cell killing and alters tumor vascularization." (PMID 38415258, 2024). "The anti-HIF-1α phytochemicals can also be explored for inhibiting angiogenesis innervating the tumor tissues." (PMID 38213742, 2024). "The central role of HIF-1α in promoting tumor progression makes it an attractive target for cancer therapy." (PMID 39493156, 2024). "Scratch wound and transwell assays corroborated the parallel role of MKLN1-AS on HIF-1α-induced pro-tumor biofunctions." (PMID 38740637, 2024).